CLEC6A (C-type lectin domain containing 6A)
Description:
Calcium-dependent lectin that acts as a pattern recognition receptor (PRR) of the innate immune system: specifically recognizes and binds alpha-mannans on C.albicans hypheas. Binding of C.albicans alpha-mannans to this receptor complex leads to phosphorylation of the immunoreceptor tyrosine-based activation motif (ITAM) of FCER1G, triggering activation of SYK, CARD9 and NF-kappa-B, consequently driving maturation of antigen-presenting cells and shaping antigen-specific priming of T-cells toward effector T-helper 1 and T-helper 17 cell subtypes (By similarity). Recognizes also, in a mannose-dependent manner, allergens from house dust mite and fungi, by promoting cysteinyl leukotriene production (By similarity). Recognizes soluble elements from the eggs of Shistosoma mansoni altering adaptive immune responses (By similarity).
Synonyms: Dectin-2; CLECSF10; hDECTIN-2; CLEC4N
Tractability: Antibody: UniProt places it where antibodies can reach, with high confidence; its Gene Ontology location is reachable by antibodies, with high confidence; UniProt predicts a signal peptide or a membrane-spanning region. PROTAC: ubiquitination databases record sites on it.
Target class: Membrane receptor
Gene: Protein-coding gene on chromosome 12 (8,455,962 to 8,478,330, forward strand). Ensembl gene ENSG00000205846.
Subcellular location: Cell membrane
Pathways (Reactome):
Immune System: Dectin-2 family
Gene Ontology:
Molecular function: calcium ion binding; carbohydrate binding; D-mannose binding; pattern recognition receptor activity; protein binding; phospholipase binding
Biological process: antifungal innate immune response; defense response to fungus; detection of yeast; innate immune response; positive regulation of canonical NF-kappaB signal transduction; positive regulation of cytokine production; positive regulation of intracellular signal transduction; positive regulation of T-helper 17 type immune response; response to yeast; stimulatory C-type lectin receptor signaling pathway
Cellular component: plasma membrane; external side of plasma membrane
Genetic constraint (gnomAD): Loss-of-function variants: 9 observed, 12.38 expected, observed/expected ratio (o/e) 0.73, 90% interval 0.44 to 1.27. The upper end of that interval is the gene's LOEUF score, 1.27, which puts it in group 5 of 6, group 1 being the genes least tolerant of losing a copy. Missense variants: 110 observed, 105.57 expected, observed/expected ratio (o/e) 1.04, 90% interval 0.89 to 1.22. Synonymous variants: 36 observed, 33.79 expected, observed/expected ratio (o/e) 1.07, 90% interval 0.82 to 1.41.
Homologues: Orthologues: chimpanzee CLEC6A (98% identical), macaque CLEC6A (91% identical), mouse Clec4n (69% identical), rat Clec6a-ps1 (67% identical), tropical clawed frog clec4e (24% identical), tropical clawed frog clec4m (24% identical), zebrafish asgr1a (24% identical), zebrafish asgr1c.2 (23% identical), tropical clawed frog asgr1 (22% identical), zebrafish asgrl1 (22% identical), Caenorhabditis elegans clec-266 (21% identical), Drosophila melanogaster tfc (19% identical), and 13 more. Paralogues in human: CLEC4C (54% identical), CLEC4A (42% identical), CLEC4D (41% identical), CLEC4E (39% identical), ASGR1 (29% identical), CLEC10A (28% identical), CLEC4M (28% identical), ASGR2 (27% identical), CD209 (27% identical), CLEC17A (25% identical), CLEC4G (24% identical), CD207 (22% identical), and 2 more.
Diseases named in the same sentence as CLEC6A in open-access papers:
CLEC6A is named in the same sentence as 60 diseases in open-access papers, as found by Europe PMC text mining. Sharing a sentence is not in itself a finding about the gene and the disease. The quoted sentences say what the papers report.
fungal infection (23 papers, 2011 to 2025). "CLRs, such as dectin-1 (CLEC7A) and dectin-2 (CLEC6A), are the main receptor group mediating antifungal recognition, and loss of their shared signalling adaptor molecule, CARD9, results in heightened susceptibility to fungal infections." (PMID 37905492, 2023). "Moreover, NOD1 and NOD2 can also compete for downstream molecules, such as RIP2 or CARD9, that are also useful for other pathways important to fight fungal infections, such as Dectin-1, Dectin-2 (CLEC6A), and RIG-I (DDX58), leading to the induction of a tailored immune response." (PMID 41249509, 2025). "Genes exclusively regulated by atRA during fungal infections included CXCL6 for A. fumigatus challenge, and the fungal pattern recognition receptor Dectin-2 (CLEC6A) as well as the type-I interferons IFNB1 and IFNA14 during C. albicans infection." (PMID 28094291, 2017).
aspergillosis (3 papers, 2019 to 2023). Aspergillosis is an infection, growth, or allergic response caused by the Aspergillus fungus. "In addition, various polymorphisms in human Dectin-2 (CLEC6A), either alone or in combination with additional genes, are associated with aspergillosis and pulmonary cryptococcosis." (PMID 31242262, 2019).
colon carcinoma (2 papers, 2022 to 2024). "In addition, liver-resident macrophages, known as Kupffer cells, were shown to limit metastasis of melanoma and colon carcinoma cell lines in the liver through dectin-2 (CLEC6A)-dependent phagocytotic activity." (PMID 38506114, 2024).
diabetes (1 paper, 2022). "To assess the possible role of Dectin-2 in the pathogenesis of diabetes, we investigated the association between Dectin-2 gene (CLEC6A) expression and insulin resistance signatures." (PMID 36078084, 2022).
Ebola (1 paper, 2023). "CLEC6A (Dectin-2) is an FcRγ-coupled receptor on macrophages and dendritic cells, proposed as a potential attachment factor for Ebola." (PMID 38235127, 2023).
parasitic infections (1 paper, 2024). "CARD9 is a critical adapter of C‐type lectin receptors (CLRs), such as Dectin‐1 (Clec7a), Dectin‐2 (Clec6a) and Mincle (Clec4e), in response to fungal, viral, bacterial and parasitic infections." (PMID 39118286, 2024).
cancer (8 papers, 2018 to 2025). A tumor composed of atypical neoplastic, often pleomorphic cells that invade other tissues. "CAMKV and MUC2 are the most enriched genes in areas of carcinoma (SSES = 1.37 and SSES = 1.29 respectively), whilst NCR1 (synonym: CD335) and CLEC6A, both selectively expressed in Natural Killer cells (NK-cells), are spatially localised to lymph nodes (SSES = 8.59 and SSES = 6.42 respectively)." (PMID 39003292, 2024).
CLEC6A also shares sentences with these, for which no sentence is quoted: infection (39 papers); systemic candidiasis (13); tumor (9); vasculitis (8); allergic disease (5); autoimmune disease (3); Candidiasis (3); chromoblastomycosis (3); colitis (3); cryptococcosis (3); inflammation (3); pneumococcal infection (3); acute myocardial infarction (2); asthma (2); autoimmune disorders (2); coccidioidomycosis (2); dermatophytosis (2); disseminated candidiasis (2); helminth infection (2); infectious disease (2); rheumatoid arthritis (2); Allergy (1); Arthritis (1); atherosclerosis (1); bladder cancer (1); breast carcinoma (1); cardiac ischemia (1); Cryptococcal meningitis (1); Hepatic fibrosis (1); histoplasmosis (1).
A further 23 diseases each share a sentence with CLEC6A in 1 paper.